MET (MET proto-oncogene, receptor tyrosine kinase)
Diseases named in the same sentence as MET in open-access papers (continued):
Sharing a sentence is not in itself a finding about the gene and the disease.
tumor (continued). "Activation of c-MET on the surface of neutrophils by HGF leads to chemotactic attraction to tumors and the release of nitric oxide to kill tumor cells, whereas conditional deletion of the MET gene in neutrophils promotes tumor growth and spread to other organs." (PMID 39201787, 2024). "Due to the significant variation in tumor characteristics and immune status among different patients, future research needs to develop personalized treatment plans and identify reliable biomarkers to accurately assess the function of the HGF/c-MET axis in each patient." (PMID 39201787, 2024). "We achieve this by summarizing the intricate crosstalk between the primary c-MET and Hh pathways within tumor cells, the downstream effects of Hh pathway activation on the TME and CAFs, and the role of SHH and HGF serves as a bridge in the context of stromal-tumor interactions." (PMID 37919751, 2023). "Since HGF activated MET/GAB1 pathway in entrectinib‐treated HCC78 cells, the timing of tumor cell lysate harvesting might not be optimal for detecting HGF‐induced MET phosphorylation." (PMID 36416133, 2023). "Hence, overactivity HGF-c-MET axis, triggered by CAF responses to RT, stimulates tumor progression." (PMID 37607935, 2023). "To examine the efficacy of the combined treatment of anti‐HER3 and anti‐MET drugs against human CRC cells, we evaluated the effects of patritumab and PHA665752 against SW1116 cells using in vitro colony formation in 3D‐culture and in vivo tumor growth in nude mice." (PMID 36751113, 2023). "So far, the best efficacy observed was based on SQ tumor model, by which one-time intra-tumoral injection of MET-CAR.CD28ζ T cells induced tumor regression without showing recurrence, which is more potent than other reported MET-CARs requiring multiple injections at tumor site to be effective." (PMID 37779207, 2023). "Notably, HGF/c-MET inhibition decreases TGF-β secretion by cancer cells, resulting in an increase in cytotoxic T-cell infiltration, thus contributing to cancer cell death in tumours." (PMID 37354984, 2023). "Therefore, we evaluated the role of MET in a 3D system obtained by coculturing GC cell lines and patient-derived gastric CAFs and found that the HGF/MET signaling axis plays a significant role in sphere formation and tumor growth." (PMID 37887325, 2023). "Moreover, interfering with CIN85 expression in ASAP2-knockdown HCC cells could almost restore tumor growth and invasion potentials, validating its role in ASAP2-induced c-MET activation." (PMID 37061723, 2023). "However, the potential use of MET-targeting therapies for tumor radiosensitization has not been fully explored yet, despite the emerging evidence that MET signaling can affect the DDR in cellular and animal models." (PMID 37188738, 2023). "Overall, elevated tumor metabolism was not necessarily accompanied by high c-MET expression." (PMID 36253641, 2023). "MET-specific CAR-T cells function through T cell signaling rather than RTK activity, therefore may overcome MET-TKI-mediated tumor resistance, and will be independent of previous treatments." (PMID 37779207, 2023). "Here we show, by genome editing of the nontransformed lung epithelial cells 16HBE, that HGF‐activated METex14 when expressed at the endogenous level, in the absence of MET amplification or other genetic alterations, transforms these cells in vitro and, importantly, induces tumour formation." (PMID 36799689, 2023). "Likewise, MET amplification mediates resistance to SRC inhibitors in various solid malignancies, while concurrent inhibition of SRC and MET produces a synergistic cytotoxic effect on tumor growth." (PMID 37120696, 2023). "In addition, IL-6 could also promote tumor cell survival, growth, proliferation, transformation, invasion, and migration by upregulating TGF-β and activating the STAT3 and HGF/c-MET pathways." (PMID 36831664, 2023).
tumor (continued). "However, these techniques, especially IHC, have limitations as they do not reflect the variability of c-MET expression over time, nor the heterogeneity within a tumour lesion or between different tumour sites." (PMID 37843660, 2023). "Because Capmatinib therapy showed efficacy in patients with NSCLC and MET is well established in the etiology of this cancer type, it would be of interest to further determine whether the THEMIS2-MET axis also exists in this tumor type." (PMID 34974522, 2022). "Besides, MET amplification and EGFR C797S were detected only in the tumor tissues." (PMID 35646096, 2022). "Mechanismly, MET protein transduces extracellular matrix signals into the cytoplasm by binding to hepatocyte growth factor/HGF ligand, and regulates many physiological processes including proliferation, dissemination, morphogenesis and survival, then contributing to the tumor process." (PMID 36713541, 2022). "Furthermore, Xing M demonstrated that activation of MAPK signaling pathway resulted in upregulation of tumor-promoting genes (e.g. VEGFA, MET, HIF1A, UPA, UPAR, TGFB1, and TSP1) as well as downregulation of tumor suppression and thyroid genes (e.g. TIMP3, SLC5A8, DAPK1, NIS, TSHR, and TPO)." (PMID 35600399, 2022). "Furthermore, sustained activity of this pathway is necessary for proliferation and maintenance of METΔex14 tumours, while forced reactivation of this pathway is sufficient to restore growth in the absence of MET activity." (PMID 35326531, 2022). "Moreover, virus-mediated overexpression of miR-199 and miR-34a has been found to lead to control of tumor growth by targeting mTOR, c-MET, HIF-1α, and CD44, as well as complete tumor regression by targeting Bcl-2 and SIRT1 in xenograft murine models of HCC, respectively." (PMID 35954176, 2022). "The binding of the receptor tyrosine kinase MET, expressed on neutrophils, by the tumor necrosis factor-alpha (TNFα), and its ligand, the Hepatocyte growth factor (HGF), drives the nitric oxide synthase (NOS) and the consequent release of the anti-tumor inflammatory mediator." (PMID 35664746, 2022). "miR-34a directly targets the 3’UTRs of numerous oncogenic mRNAs, including ARAF, CD44, CD117, CDK4, c-Met, cyclin D3, cyclin E2, E2F3, Fra-1, Jagged1, MCM2/5, MET, MYCN, Notch1/2, PIK3R2, PLK1, Smad4, SIRT1/6, and VEGFA, which may contribute to its tumor-suppressive role." (PMID 35961977, 2022). "Among these, MET is overexpressed in advanced GC, regardless of tumor differentiation." (PMID 35884507, 2022). "Nonselective c-MET inhibitors (e.g., tivantinib and cabozantinib) may exert anti-tumor effects, mainly owing to the inhibition of non-c-MET targets, and an “off-target” effect is associated with increased toxicity." (PMID 35000616, 2022). "Aberrant activation of the MET/HGF pathway is involved in the development and metastatic progression of various tumors, and this pathway constitutes the mechanism by which cancer patients acquire resistance to targeted treatment and attenuates tumor response to immunotherapy." (PMID 36341335, 2022). "We further compared the relative expression of these molecules in 14 cancer types containing paired tumor and normal samples and found that approximately half of the autophagy regulators showed elevated expression in different cancers, including BIRC5, RIPK2, MET, ITGA6, BCL2L1, CASP4, etc.." (PMID 36261830, 2022). "Interestingly, molecular analysis review conducted on tumor samples with the new v12.3 classifier showed a match with pediatric RTK1 type, subtype B, and a complex copy number variation (CNV) with CDK6 and MET amplification, and a platelet-derived growth factor A (PDGFRA) gain." (PMID 35204463, 2022). "Finally, to further verify whether the tumor invasiveness promoted by MACC1 was dependent on MET, we treated PC cells with JNJ-38877605, a selective inhibitor of MET." (PMID 36333284, 2022).
tumor (continued). "Importantly, findings from this study supported using blood tests to monitor the emergence of MET amplification in patients undergoing anti-EGFR therapies, as the amplification of the MET locus has been present in circulating tumor DNA before any clinical evidence of relapse." (PMID 34326875, 2021). "In consequence, particularly in cases with important stroma and/or inflammatory component, the mRNA expression levels obtained by nCounter might reflect the level of MET expression in the whole tumor rather than only in cancer cells." (PMID 33236532, 2021). "To develop an assay that could be used to evaluate clinical formalin-fixed paraffin-embedded (FFPE) tumor specimens, we evaluated EGFR:MET transcript ratios through BaseScope, an RNA-based in situ hybridization assay in which fluorescent signal area acts as a surrogate for RNA transcript expression." (PMID 34516823, 2021). "Another possible reason is that the tissue collected at the time of initial diagnosis may not have provided a good estimate of the level of MET expression because tumor characteristics may be altered after chemotherapy." (PMID 34557411, 2021). "Putative oncogenic and targetable mutations could be found in individual tumor samples in FGFR2 (SNUC, SNSCC non-keratinizing), FGFR3 (SNSCC-associated with ISP), MAP1K2 (SNAC), MET (ISP-associated SNSCC), MAP2K1 (SNAC) and HRAS (SNSCC keratinizing and ITAC)." (PMID 34885191, 2021). "JQ1 had little effect on TP63 and MET expression in ALDHlowCD44high non-stem tumor cells." (PMID 34172737, 2021). "The MET exon 14 skipping mutation inhibitors capmatinib, tepotinib, and savolitinib have been proposed for the treatment of adult patients with metastatic NSCLC whose tumors harbor this mutation, irrespective of tumor histology." (PMID 34425853, 2021). "Thus, MET, OAS1, and OASL were distinctly correlated to tumor immune microenvironment." (PMID 33869254, 2021). "As previously reported, multiplex sequencing of tumour samples from patients with gastroesophageal cancer is feasible and does identify potentially actionable targets, in most cases amplification of known oncogenes such as ERBB2, EGFR, FGFR1–3, KRAS and MET, in a significant proportion of patients." (PMID 34794033, 2021). "Importantly, concordant high MET RNA‐ISH/c‐MET IHC protein expressing tumours demonstrate no significant survival compared to the low MET RNA‐ISH/c‐MET IHC protein expressing patients." (PMID 34428346, 2021). "However, there is a certain relationship between the acquired resistance of EGFR-TKIS and c-MET gene amplification in about 20% of tumor cell lines without c-Met gene amplification." (PMID 34122599, 2021). "Furthermore, neither tumor mutation burden nor co-occurring MET and EGFR mutations were significantly correlated with the size of the MET amplification." (PMID 34758872, 2021). "However, the c-MET inhibitor did not have any significant effect either on primary tumor growth, or on liver colonization ability of the cetuximab sensitive PE/CA-PJ41 cancer cells." (PMID 34257586, 2021). "Additionally, MET, TGFα, FGF2, CD151, and MMP3 are some of the oncogenic targets of miR-152 in human cancers; by targeting these genes, miR-152 leads to inhibition of cell proliferation and tumor metastasis." (PMID 33680048, 2020).
tumor (continued). "This raises the possibility that c-MET inhibitors could be used in patients with non-MET dependent tumors as well as those with tumor cells with aberrant activity." (PMID 32117721, 2020). "Furthermore, the xenograft mouse model supports our hypothesis that NU1074 plus SU11274 displays a significant reduction of tumour growth in a cell line with low levels of BRCA1/2 and c‐MET." (PMID 32686903, 2020). "Indeed, an abstract from a pre-clinical study of a c-MET targeting therapeutic antibody ARGX-111 indicates that the drug can diminish c-MET positive MDSCs, suggesting a role of this drug in treating c-MET positive tumors and altering c-MET activity of cells in the tumor microenvironment." (PMID 32117721, 2020). "In addition, circ-PDE8A excreted by the tumor can be released into the blood circulation through exosome transport, acting as ceRNA of miR-338, regulating MACC1 and promoting invasive metastasis through MACC/MET/ERK or AKT pathways." (PMID 33324638, 2020). "However, some actionable targets can be present in other genes (notably MET, RET, NTRK, and HER2), allowing inclusion into clinical trials of patients with EGFR, ALK, ROS1, and BRAF wild-type tumors with less than 50% PD-L1-positive tumor cells." (PMID 32294880, 2020). "Basic science supported a key role of c-MET in NSCLC patients developing resistance to EGFR TKIs, supporting design of JNJ-61186372 (EGFR × c-MET BsAb) and patient selection criteria leading to demonstrated anti-tumor activity in NSCLC patients with resistance to EGFR TKIs." (PMID 32989604, 2020). "This indicates that HER3 overexpression, even after the pronounced increase in HER3 levels upon treatment with MET inhibitors or siRNA, is insufficient to compensate for the blocking of MET-dependent pathways in tumor cells that do not endogenously express heregulin." (PMID 33374770, 2020). "Immunoblotting of bulk tumor lysates showed that maturation of c-MET was not fully blocked." (PMID 32161259, 2020). "However, the analysis of post-afatinib progression sites of one patient revealed a MET amplification which was not present in the analyzed tumor before treatment." (PMID 31557260, 2019). "Previously reported Histone H3 lysine 27 acetylation (H3K27) ChIP-sequencing (ChIP-seq) data of an IDH-mutant cell line and tumor tissue also showed peaks associated with an active promoter region around the transcription start site of MKNL1, but not around that of MET." (PMID 30760837, 2019). "Tivantinib (ARQ 197) exhibits anti-tumor activity independent of MET inhibition." (PMID 31867280, 2019). "Compared to the vehicle group, MLN0128 or PD901 monotherapy as well as combination treatment group led to a slight decrease of CD34 immunoreactivity, indicating that inhibition of angiogenesis is not a major mechanism for the anti-tumor activities exerted by MLN0128 or PD901 in AKT/c-MET mice." (PMID 31277283, 2019). "Our data support the idea that simultaneous targeting of EGFR and MET could be a promising therapeutic strategy inhibiting not only tumor cell growth but also its metastasis." (PMID 31649529, 2019). "Lack of MET amplification, Met and phosphorylated Met levels, and insensitivity to the Met inhibitor crizotinib in pre and post-dacomitinib GSCs support the notion that Met does not play a significant role in the emergent tumour resistance in the current case." (PMID 30644426, 2019). "Furthermore, we could examine the proportion of specific biomarker-expressing tumor cells in each PDC, such as HER-2, EGFR, and MET etc. before anti-cancer drug-sensitivity test." (PMID 31850215, 2019). "Expression of NFκB or p21 were elevated along with MET in a tumor specific manner, but lacked overall correlation suggesting that MET-MAPK could potentially be a relevant mechanism in cTCL." (PMID 29854308, 2018). "Unlike other c-MET inhibitors, LZ8 prevents the tumor progression in HCC without c-MET dependent." (PMID 30360560, 2018).
tumor (continued). "Hence, we quantified c-MET throughout the whole tumor sample rather than in specific sub-populations." (PMID 29463215, 2018). "Based on our findings, we proposed that the antitumor effect of NZ001 on MET amplified MHCC-97H xenografts was likely to be mediated by inhibiting tumor angiogenesis through VEGFR2 inhibition (anti-angiogenesis effect) and by directly inhibiting tumor cell proliferation (anti-proliferation effect)." (PMID 29712569, 2018). "While we have focused on mutations in EGFR, resistance alterations in other genes, such as MET amplification, could render a tumor non-responsive to any EGFR targeted therapy." (PMID 30481207, 2018). "The identification of this unique molecular interaction between SPRY2 and MET that functions to regulate the oncogenic properties of RMS raises the possibility of leveraging it for future therapeutic interventions in RMS and other tumor types where MET is aberrantly activated." (PMID 29445192, 2018). "To investigate whether validated targets of miR-34a were modulated by its synthetic mimic in DMPM cells, we assessed protein expression levels of c-MET, AXL, and CDK6 considering their established role in the control of cell proliferation and apoptosis in different tumor types." (PMID 28100259, 2017). "Regarding suppression of the tumor function by dasatinib, in function studies of ASPS, a genome-wide location analysis of ASPS tumor samples and cell lines expressing ASPSCR1–TFE3 defined a subset of approximate 400 genes as putative regulated direct targets of ASPSCR1–TFE3, including c-MET." (PMID 28945796, 2017). "Furthermore, we identified elevated HGFR expression in 6 and MET copy number increase in 5 metastases out of 15 ccRCCs without elevated expression of HGFR or copy number gains of MET in the primary tumor." (PMID 27894094, 2017). "Beside p.T790MEGFR and MUTKRAS, other mechanisms of acquired resistance not evaluated in our study have been described in tumor re-biopsies after EGFR-TKI progression, including actionable mutations of MET, HER2, PIK3CA or transformation into small cell histology (3%)." (PMID 26799287, 2017). "We also explored the effect of c-MET antibody in the inhibition of tumor growth in vivo, however, it proved difficult (data not shown), which might be due to intrinsic agonistic activity." (PMID 28404966, 2017). "However, treatment with tivantinib, a MET inhibitor, only achieved stable disease (no tumor shrinkage) in two ASPS patients." (PMID 28679123, 2017). "However, dual combinations i.e HGF inhibition + c-MET blockade, HGF inhibition + gemcitabine and c-MET blockade + gemcitabine did not exhibit any additive effect in terms of tumor reduction." (PMID 29100344, 2017). "For example, the afatnib/trametinib combination elicited a complete response for a representative heterogeneous MET-negative tumor cell population comprised of (89% EGFRL858R, 10% EGFRL858R BRAFV600E, 1% EGFRL858R, T790M) compared to rapid progression for its MET activated analog." (PMID 28287179, 2017). "Theoretically, our BsAb could inhibit tumor progression, migration, metastasis, and angiogenesis by blocking c-MET, and can also rescue systemic T cell function by blocking PD-1 in cancer cells overexpressing c-MET and PD-L1." (PMID 28404966, 2017). "Cabozantinib was shown to result in more extensive anti-tumor activity in animal models than a multi-kinase inhibitor targeting VEGFR2 without c-MET inhibition, and to suppress metastasis, angiogenesis and tumor growth across a variety of tumor xenograft models." (PMID 26762579, 2016). "To exclude MET expression in rare tumor areas undergoing E/N-cadherin switching indicative for epithelial-mesenchymal transition, we determined MET expression in consecutive tissue slides of independent N-cadherin positive tumor areas, which likewise did not demonstrate MET staining." (PMID 27105539, 2016).